IL1B (interleukin 1 beta)
Diseases named in the same sentence as IL1B in open-access papers (continued):
Sharing a sentence is not in itself a finding about the gene and the disease.
tumor (continued). "RT-qPCR analysis indicated that the expressions of the proinflammatory cytokines (TNF-α, IL-6, and IL-1β) and TLR4 of tumor tissues from group 2 were markedly increased at mRNA level after LPS treatment, compared with those of group 1 or 3 without LPS treatment." (PMID 25179302, 2014). "Besides interfering with natural tumor control, NLRP3 inflammasome-mediated IL-1β has been described to attenuate anti-tumor effects of chemotherapeutic agents, gemcitabine (Gem), and 5-fluorouracil (5FU)." (PMID 25071785, 2014). "Likewise, expression of IL-1β and inhibitors of Wnt signaling, such as DKK-1, in tumor cells have been reported to be involved in malignant osteolysis through both an activation of osteoclastogenesis and an inhibition of bone formation." (PMID 25490771, 2014). "IL-1β acts together with VEGF in mounting and maintaining tumor-mediated angiogenesis." (PMID 24734023, 2014). "We have shown that IL-1β inhibition stably reduces tumor growth, by limiting inflammation and inducing the maturation of MDSCs into M1 macrophages, which do not promote tumor invasiveness and can be cytotoxic/cytostatic for tumor cells." (PMID 24734023, 2014). "Furthermore, antibodies against IL-1β and TNF-α receptors added to media conditioned by macrophage/tumor cell co-cultures were observed to inhibit the enhanced expression of VEGF-C in macrophages." (PMID 25120672, 2014). "Notably, these cells maintained high expression of FABP4 and IL-1β, further strengthening the link between FABP4/IL-1β axis and tumor invasiveness." (PMID 24240026, 2013). "Analyses of purified tumor-infiltrating CD45+ cells indicated that Lov treatment increased mRNA levels for M1 markers, which was statistically significant for IFNγ and IL-1β, whereas it downregulated M2-like markers (with significant differences for IL-10, CD206 and CCL22)." (PMID 24317954, 2013). "We have studied in detail the role of IL-1β in tumor-mediated angiogenesis, which is almost non-existent upon injection of tumor cells into IL-1β KO mice or following neutralization of IL-1β in WT mice." (PMID 23847618, 2013). "IL-1β was not increased in H. pylori infected samples, but was increased in 10 of 24 tumor samples up to 31 fold when compared to normal tissues." (PMID 23365642, 2013). "Tumor-mediated angiogenesis is inhibited if either IL-1β or VEGF are neutralized and it does not occur in IL-1β KO mice." (PMID 23847618, 2013). "Our previously studies indicated the inhibitory effect of S. striata extract on pro-inflammatory mediators production by macrophages including Nitric Oxide (NO), TNF-α, IL-1β and PGE2 and also suppressive effect on matrix metalloproteinases in Wehi-164 tumor cell line in vitro." (PMID 23837463, 2013). "The synchronous evaluation of 12 cytokines showed that preoperative plasma levels of the proinflammatory cytokines IL-6, IL-8, IL-1β, TNFα were significantly lower in healthy donors versus CRC patients and that such differences progressively increase with tumor stage." (PMID 24040252, 2013). "It further supports that IL-19 not only directly facilitates cell proliferation, cell migration, and metastasis but it also prompts the expression of IL-1β, IL-6, TGF-β, MMP-2, MMP9, CXCR4, and fibronectin, which supply of a microenvironment for tumor growth and metastasis." (PMID 23710200, 2013). "Only PK and immE7 cells constitutively expressed substantial amounts of the 31 kDa pro-IL-1β form, while it was reduced in E6-positive immortalized keratinocytes or even absent in the tumor cell lines." (PMID 23935506, 2013). "To determine if FABP4, IL-1β, and HMOX-1 are involved in tumor cell adaptation to adipocyte-derived factors, we cultured PC3 cells in media containing gradually increasing amounts of Adipo CM (gradient of 5-25% over multiple passages) and then maintained them long-term in 25% Adipo CM." (PMID 24240026, 2013).
tumor (continued). "Although the functional role of IL-1β in the regulation of tumorigenesis, tumor invasiveness, metastasis, and tumor-host interactions has been characterized, the main role of EGF-induced IL-1β expression remains unclear." (PMID 23383347, 2013). "Additional blocking experiments with anti-IL-1β resulted in significant inhibition of the tumor cell adhesion in the model, but they did not test the effect in vivo." (PMID 22296757, 2012). "We showed that HCT116 cells expressing dnTCF4 failed to stimulate peripheral blood monocytes to secrete IL1β, confirming that Wnt signaling is required for the expression of the tumor derived factor that stimulates macrophages." (PMID 23029025, 2012). "The combination of decreased TNFα, IL-1β, and COX-2 found in the PDTC treated epidermis provides compelling evidence that Hr is capable of modulating epithelial inflammation via regulation of the NFκB pathway and thereby further contributes to tumor promotion." (PMID 22761871, 2012). "In the case where the tumor cell secretes its own IL-1β, then the phenomenon can occur without injury, or in an enhanced way at sites already undergoing remodeling." (PMID 22296757, 2012). "In addition to GM-CSF, IL-1β, IL-6, and IL-17, inflammatory cytokines frequently induced after therapies can also drive MDSC expansion in tumor." (PMID 22778760, 2012). "IL-1β/TGF-β-induced neurospheres display up-regulated expression of stemness factor genes (nestin, Bmi-1, Notch-2 and LIF), and increased invasiveness, drug resistance and tumor growth in vivo: hallmarks of GSCs." (PMID 22330721, 2012). "B16F10 cell-derived IL-1β significantly abolished tumour growth in wild-type syngeneic C57BL/6 mice and nude mice at days 29 and 36, respectively, although the tumour growth was similar during the first 3 weeks for B16F10-IL-1β, B16F10-pro-IL-1β and B16F10-vector cells." (PMID 23065753, 2012). "In contrast, the proportion of macrophages, dendritic cells, T cells, B cells and NK cells was not affected by the IL-1β-secreting tumours." (PMID 23065753, 2012). "Since IL-1β does not directly inhibit tumour cell proliferation, the underlying mechanisms involved in the IL-1β-mediated inhibitory effect in vivo most likely occur through an indirect paracrine manner." (PMID 23065753, 2012). "In addition, the tumour size of B16F10-IL-1β- and B16F10-vector tumours was similar in Il1r1−/− mice, indicating that the inhibiting effect of tumour-derived IL-1β on tumour growth was dependent on the host response." (PMID 23065753, 2012). "In such a setting, inflammatory cells that were recruited to the tumor site in response to chemokines such as CCL2 and CCL5 continue releasing the inflammatory cytokines TNFα and IL-1β, whose activities further promote the release of the cancer-related chemokines." (PMID 24213226, 2012). "We found that 25 out of the 33 tested inflammasome-related genes were detectable by quantitative RT-PCR, and 8 of them (CIITA, NLRC4, NLRP3, NLRP7, AIM2, RIG-I, ASC and IL-1β) were overexpressed (fold change, >2) in NPC tumour samples, compared to adjacent normal samples." (PMID 23065753, 2012). "Although a number of other TDF have been linked to diverse elements of MDSC biology, namely VEGF, GM-CSF, IL-1β, IL-6, PGE2, IFN-γ, SCF or IL-17, none have been rigorously tested to explain the connection between granulocytic MDSC response and tumor growth." (PMID 22110722, 2011). "Yet, in opposition to their study, we did not observe any effect of IL-1β treatment on sHLA-E production by tumor cells, probably due to a low expression of IL-1 receptor (IL-1R1) by the tumor cell lines tested in our study." (PMID 21712991, 2011). "A high incidence of expression in the tumor cells was also denoted for TNFα and IL-1β in the three groups of cancer patients: DCIS, IDC-no-relapse and IDC-with-relapse." (PMID 21486440, 2011).
tumor (continued). "In our studies, BALF CSF-1 levels were nearly undetectable while IL-1β levels were significantly higher in tumor-bearing lungs vs. naïve (data not shown)." (PMID 21699731, 2011). "Under such conditions, TNFα & IL-1β would not act on the tumor cells to promote the release of CCL2 & CCL5, leading to lack of associations between the two cytokines and CCL2 & CCL5." (PMID 21486440, 2011). "Since IL-1β has been shown to induce the expression of MCP-1 leading to chronic inflammation, we hypothesized that IL-1β-may induce the expression of MCP-1 and IL-10 in HR tumor cells." (PMID 21978632, 2011). "The cytokine IL1β, identified by the IPA analysis as linkedto the activation of the pro-metastatic chemokines CX3CL1 andCCL20, was up-regulated in the tumour cellpopulations PIN and H-PCA, whereas the expression ofIL1R1, which mediated the activity ofIL1β, follows an opposite trend." (PMID 21479216, 2011). "In parallel, we determined the expression of CCL2, CCL5, TNFα and IL-1β in normal breast epithelial duct cells that were in proximity to the tumor cells in biopsies of patients with DCIS, IDC-no-relapse and IDC-with-relapse." (PMID 21486440, 2011). "Here we present data which demonstrate that macrophages and IL-1β protect tumor cells from TRAIL-induced apoptosis through induction of Wnt signaling in tumor cells, as cells expressing dnTCF4 were not protected from TRAIL-induced apoptosis by macrophages." (PMID 20661477, 2010). "It has been shown that the ability of LPS, an inducer of IL-1β, to promote the growth of CT26 tumors strictly depends on functional NF-κB signaling, and that inhibition of NF-κB converts inflammation-induced tumor growth to TRAIL-mediated tumor regression." (PMID 20661477, 2010). "It was reported that IL1B increased the expression level of TGM2, which might be involved in establishing a barrier to tumor spreading." (PMID 20142997, 2010). "One possible explanation might be that cytokines such as, TNF-α, IL-1β and VEGF produced from tumor microenvironment enhanced the expression of CXCR7." (PMID 20380740, 2010). "The third connection including TGM2, IL1B, and PLAU was suggested to be tumor invasion." (PMID 20142997, 2010). "To establish whether IL-1β is required for macrophage mediated protection of tumor cells from TRAIL-induced apoptosis, we first silenced IL-1β in THP1 macrophages." (PMID 20661477, 2010). "The addition of exogenous IL-1β prevented the ability of vitamin D3 to regulate TRAIL induced apoptosis, confirming that vitamin D3 restored the sensitivity of tumor cells to TRAIL by inhibiting the release of IL-1β from macrophages, and not by affecting signaling by IL-1β." (PMID 20661477, 2010). "Vitamin D3 inhibited the ability of tumor cells to stimulate IL-1β release from macrophages and, subsequently, vitamin D3 treated macrophages failed to induce Wnt signaling in tumor cells." (PMID 20661477, 2010). "High levels of serum IL-1β and IL-6 levels correlated with delayed tumor progression in animals bearing 4T1 tumors treated with mcr84 and GU81, whereas low levels of these cytokines corresponded to tumor progression." (PMID 19888452, 2009). "IL-1β, IL-6, IL-8, IL-10, IL-12, MCP-1 and MIP-1β were abundant in high-grade tumours." (PMID 17261184, 2007). "However, several cytokines produced by monocytes (IL-1β, IL-6 and MCP-1) or macrophages (such as IL-1β, IL-6, IL-8, MIP-1β and TNF-α) are highly expressed by the tumour." (PMID 17261184, 2007). "However, IL-1β, IL-6, IL-8, IL-10, IL-12, MCP-1 and MIP-1β were more abundant in high-grade tumours than in low-grade tumours." (PMID 17261184, 2007). "IL-1β has been shown to be the predominant inducer of GCP-2 in non-tumour cells such as mesenchymal cells and endometrial stromal cells." (PMID 16721367, 2006).
tumor (continued). "Tissue cytokine (IL-1β, IL-6, IL-8, and TNF-α) mRNA and protein levels were found at similar concentrations within tumour tissues with a chronic inflammatory cell infiltrate and tumour samples with lymphoid aggregates alone." (PMID 17088911, 2006). "The addition on day 0 of interleukin 1 beta (IL-1 beta) to MEMNCs cultured in the presence of IL-2 was effective in promoting the growth of CD3+ CD8+ cells and augmenting the cytotoxicity against autologous tumour." (PMID 7917907, 1994). "Pro-inflammatory cytokines such as interleukin-1 beta (IL-1β), interleukin-6 (IL-6), and tumor necrosis factor-alpha (TNF-α)—primarily secreted by macrophages and other immune cells in the TME—are instrumental in both tumor progression, systemic immune modulation, and renal function." (PMID 41301732, 2025). "Consistent with the results obtained from in vitro assays, IHC staining disclosed a significantly suppressed expression of senescence marker P21 and SASP cytokines like IL6 and IL1β in tumor samples, regardless of GDC-0879 mono- or combined therapy with anti-PD1." (PMID 40781221, 2025). "In addition, MICs produce inflammatory mediators such as IL-1β, TNF-α, and IL-6, which may initially help initiate an anti-tumor immune response." (PMID 39897552, 2025). "Mechanistic studies in breast cancer models have demonstrated that mature adipocytes co-cultured with tumor cells acquire an activated phenotype, characterized by upregulation of matrix metalloproteinases (e.g., MMP-11) and pro-inflammatory cytokines, such as interleukin (IL)-6 and IL-1β." (PMID 40422235, 2025). "Notably, HDM-driven tumor promotion was abolished in Il17a -/- but not Il1b -/- mice, identifying IL-17A as a critical mediator." (PMID 41040138, 2025). "Given the excellent efficacy of the triple treatment in inhibiting tumor progression, it is not surprising to us since TGFβ-1, IL-1β, and IL-10, and IL-30 are key mouse Th2, Th17, and Treg differentiation cytokines that have been linked to immune suppression during cancer development." (PMID 40104170, 2025). "Targeting TREM2 or IFITM limited MMRd tumor growth, but blocking IL1B was not beneficial." (PMID 40027748, 2025). "Moreover, the Gomisin B + cisplatin group and the YGS + cisplatin group could promote tumor tissue apoptosis and reduce the levels of inflammatory factors TNF-α, IL-1β, and IL-8." (PMID 40247422, 2025). "Transcriptional programs centered on IL1B/CXCL5 and LGALS3/IDO1 define distinct immune phenotypes that may guide future combination strategies targeting both effector and suppressive arms of the tumor immune response." (PMID 40723289, 2025). "Additionally, transient increases in inflammatory cytokines such as IL-6 and IL-1β following DSS administration have been reported, and these cytokines are known to promote tumor cell proliferation, immune evasion, and defective DNA repair, thereby facilitating tumorigenesis." (PMID 41285904, 2025). "Finally, IL-1β stimulation induces TEV release with biological properties similar to OR TEVs, thus leading to cancer invasion and immune suppression and suggesting that inflammation can promote tumor spreading." (PMID 40725070, 2025). "In addition, the expression of several pro-inflammatory cytokines and chemokines such as IL-1β, IL-22, TNF-α, CXCL1, CXCL2, CCL17 and CCL20 were reduced in IL-38KO mice, suggesting that IL-38 promotes tumour growth and development in cSSC through promoting an inflammatory tumour environment." (PMID 40057603, 2025). "Particularly, M1-type TAMs secrete a repertoire of pro-inflammatory cytokines including IL-1β, IL-6, and tumor necrosis factor-alpha (TNF-α), alongside generating ROS that potentially inflict DNA damage, thus catalyzing innate immune responses conducive to the obliteration of tumor cells." (PMID 40664640, 2025).
tumor (continued). "MNDA+ TANs with anti-tumor activity (N1-phenotype) are found to be abundantly infiltrated by MTC with benefit of increased blood perfusion, and these TANs are characterized by enhanced cytotoxicity, ameliorated hypoxia, and upregulated IL1B, activating T&NK cells and fibroblasts via IL1B-IL1R." (PMID 40360503, 2025). "Interestingly, studies have shown that the release of bioactive IL-1β within tumours does not depend on the activation of inflammasomes, caspase-8, the pore-forming protein GSDMD, or mixed lineage kinase domain-like protein (MLKL)." (PMID 40234383, 2025). "With progressive ADM expression decline, transcriptional levels of pro-tumorigenic inflammatory cytokines IL1B and CX3CL1 demonstrated gradual downregulation, suggesting elevated ADM expression may accelerate tumor progression through pro-inflammatory microenvironment enrichment." (PMID 41450464, 2025). "While our data highlight the role of IL-1β induction in tumor cells, we cannot entirely rule out the potential contributions of other immune or stromal cells within the tumor microenvironment to tumor IL-1β expression." (PMID 39801513, 2024). "Furthermore, IL-1β induces VEGF secretion, which also spurs tumor expansion and spread." (PMID 38957317, 2024). "HCH could reverse the pathological lung tissue into approximately normal, the protein expression of Ki-67, VEGF and SMC3 were all reduced, the ROS level was reduced andSOD level was increased, the levels of IL-1β, IL-8, IL-13 and TNF-α were all reduced, the weights of tumor were reduced." (PMID 39211045, 2024). "This loop could lead to the sustained release of IL-1β from tumor cells and the subsequent induction of IL-1β expression in other tumor cells not directly exposed to B cells." (PMID 39801513, 2024). "M1 macrophages secrete many cytokines, including interleukin 1-beta (IL-1β), tumor necrosis factor alpha and beta (TNF-α and TNF-β), and interleukin 6 (IL-6), and are regarded as anti-tumor or pro-inflammatory, while M2 are considered as pro-tumor or anti-inflammatory." (PMID 38842752, 2024). "For example, blocking IL1B expression in IL1B+ macrophages could prevent the production of angiogenesis-promoting MC4 via the IL1B/ADRB2 pathway, resulting in the inhibition of tumor growth, a reduction in the TNF+/VEGFA+ ratio, and an increase in patient prognosis." (PMID 39840068, 2024). "This suggests that, while plasma IL-1β levels might not reflect the local tumor activity, mRNA levels could serve as a more accurate marker of the biological activity of the tumor." (PMID 39766795, 2024). "In particular, our investigation into its role in immune escape mechanisms uncovered a significant positive correlation with immune-suppressive cytokines (TGF-β, IL-10, and IL-1β) and a negative correlation with anti-tumor cytokines (IFN-γ, IL-2, and TNF-α) in metastatic lung cancer." (PMID 38951802, 2024). "Notably, plasmatic IL-1β levels have been shown to be increased in RDEB patients, which may promote immune suppression and facilitate tumor progression." (PMID 39001538, 2024). "Moreover, other cytokines such as IL‐6, IL‐1β, VEGF, and IL‐10 have been correlated with poor prognosis in cancer patients due to their role in regulating myeloid cell (e.g., MDSCs) differentiation and recruitment to the tumor." (PMID 37681284, 2024). "Interestingly, S1PR1 knock-out in TAMs strongly reduced IL-1β level and lymphangiogenesis, though it did not affect tumor development in methylcholanthrene (MCA)-induced fibrosarcoma murine model." (PMID 38576612, 2024). "Mechanically, PTA reinforces the anti-tumor ability of Th9 cells primarily through upregulating interleukin (IL)-1β and subsequently activating the downstream STAT1/IRF1 pathway, which could be effectively blocked by intercepting IL-1β signaling." (PMID 38760861, 2024).